RMP64 (ribonuclease MRP subunit p64)
Description:
Specific component of the MRP ribonucleoprotein endoribonuclease, Rnase/Mrp complex, a ribonucleoprotein complex involved in pre-rRNA processing. May play a role in cortex development as part of the Notch signaling pathway. Downstream of Notch may repress the expression of proneural genes and inhibit neuronal differentiation thereby maintaining neural progenitors. May also play a role in preimplentation embryo development (By similarity).
Synonyms: C3orf17; NEPRO; DKFZP434F2021; NET17; ANXD3
Tractability: PROTAC: ubiquitination databases record sites on it.
Gene: Protein-coding gene on chromosome 3 (113,002,444 to 113,019,861, reverse strand). Ensembl gene ENSG00000163608.
Subcellular location: Nucleus; Nucleus, nucleolus
Subcellular location (Human Protein Atlas): Nucleoli; Nucleoplasm
Gene Ontology:
Biological process: RNA processing; negative regulation of neuron differentiation; positive regulation of Notch signaling pathway
Cellular component: nucleolus; nucleoplasm; nucleus; ribonuclease MRP complex
Genetic constraint (gnomAD): Loss-of-function variants: 30 observed, 35.54 expected, observed/expected ratio (o/e) 0.84, 90% interval 0.63 to 1.14. The upper end of that interval is the gene's LOEUF score, 1.14, which puts it in group 5 of 6, group 1 being the genes least tolerant of losing a copy. Missense variants: 549 observed, 599.82 expected, observed/expected ratio (o/e) 0.92, 90% interval 0.85 to 0.98. Synonymous variants: 191 observed, 214.05 expected, observed/expected ratio (o/e) 0.89, 90% interval 0.79 to 1.01.
Homologues: Orthologues: chimpanzee NEPRO (99% identical), macaque NEPRO (94% identical), pig NEPRO (80% identical), dog NEPRO (78% identical), rabbit NEPRO (77% identical), guinea pig NEPRO (77% identical), mouse Nepro (66% identical), rat Nepro (66% identical), tropical clawed frog nepro (34% identical), zebrafish nepro (27% identical).
Diseases named in the same sentence as RMP64 in open-access papers:
RMP64 is named in the same sentence as 12 diseases in open-access papers, as found by Europe PMC text mining. Sharing a sentence is not in itself a finding about the gene and the disease. The quoted sentences say what the papers report.
anauxetic dysplasia (1 paper, 2026). A spondyloepimetaphyseal dysplasia that is characterized by the prenatal onset of extreme short stature, an adult height of less than 85 cm, hypodontia, and mild mental retardation. "Notably, people with anauxetic dysplasia have been found to have missense mutations affecting residues R94 and L145 of RMP64, consistent with RMP64 being a subunit of RNase MRP58." (PMID 41136609, 2026).
RMP64 also shares sentences with these, for which no sentence is quoted: cancer (2 papers); Hearing impairment (2); Alzheimer disease (1); cataract (1); connective tissue disorder (1); Crohn disease (1); deafness (1); microcephaly (1); osteoarthritis (1); rheumatoid arthritis (1); urolithiasis (1).